MIR588 (microRNA 588)
Synonyms: hsa-mir-588; MIRN588
Gene: MicroRNA gene on chromosome 6 (126,484,631 to 126,484,713, forward strand). Ensembl gene ENSG00000207632.
Homologues: Orthologues: chimpanzee ptr-mir-588 (100% identical).